EZH2 (enhancer of zeste 2 polycomb repressive complex 2 subunit)
Diseases named in the same sentence as EZH2 in open-access papers (continued):
Sharing a sentence is not in itself a finding about the gene and the disease.
myelofibrosis (27 papers, 2011 to 2025). A partial or complete replacement of the bone marrow stroma by fibrous tissue. "In more details, NFE2, SRSF2 and EZH2 were associated with secondary myelofibrosis, while SRSF2 and IDH1/2 were associated with AML/MDS transformations." (PMID 40533498, 2025). "EZH2 mutations have been identified in 6–13% of myelofibrosis and are associated with poor survival." (PMID 32823933, 2020). "The presence of EZH2 mutations is indicative of more progressive disease as highlighted above in myelofibrosis and by Lasho and McNamara in leukemic transformation with 15% and 7% identified in each cohort respectively." (PMID 32823933, 2020). "Of note, Lin28b, but not Plag1, was also demonstrated to be up-regulated following loss of Ezh2 during the accelerated development of Jak2V617F-mediated myelofibrosis." (PMID 30890554, 2019). "EZH2 loss-of-function mutations were correlated with poor prognosis also in a cohort of patients with myelofibrosis." (PMID 26497210, 2016). "Two studies reported the presence of different EZH2 inactivating mutations in myeloid hemopathies, such as myelofibrosis, chronic myelomonocytic leukemia (CML), atypical chronic myelogenous leukemia and MDS." (PMID 26497210, 2016). "Mutations of ASXL1 and EZH2, for instance, have identified in myelofibrosis." (PMID 37760623, 2023). "Moreover, loss of Ezh2 accelerates the development of myelofibrosis and decreases survival in Jak2-V617F–driven MPN and Runx1 mutated MDS, identifying EZH2 as a tumor suppressor." (PMID 30890554, 2019). "In mice models, the MPN phenotype induced by JAK2 V617F was accentuated in JAK2 V617F/EZH2 (wild type/wild type) mice, resulting in very high platelet and neutrophil counts, more advanced myelofibrosis, and reduced survival." (PMID 35562964, 2022). "ASXL1, EZH2, and SRSF2 mutations were associated with poor prognosis in primary myelofibrosis (PMF), and the patients could easily transform to s‐AML." (PMID 36799265, 2023). "A screening of 518 patients suffering from PMF and post-PV/TE myelofibrosis found the EZH2 mutation in nearly 1% of post-PV myelofibrosis without significantly impacting overall survival." (PMID 35456443, 2022). "Despite that EZH2 is commonly overexpressed in high risk MDS and AML, the observation that loss of function mutations affect patients with MDS/MPN, myelofibrosis, and various MDS entities highlights the fact that EZH2 can function as tumor suppressor and oncogene depending on the cellular context." (PMID 36338673, 2022). "EZH2 seems to act as a tumor suppressor in MPN, and a high number of loss of function mutations have been identified that synergizes with JAK2V617F in initiating MPN and promoting myelofibrosis." (PMID 34440731, 2021). "Furthermore, EZH2-loss-of-function mutations were associated with a poor outcome in MDS, CML and myelofibrosis." (PMID 34202528, 2021). "Activated TNFα pathways were also confirmed by RNA-seq analysis in patients suffering from EZH2- or DNMT3A-deficient myelofibrosis compared to non-mutant controls." (PMID 32604862, 2020). "However, in 2010, loss-of-function mutations of EZH2 were observed in myeloid malignancies, most frequently affecting patients with MDS/MPN (10–13%), myelofibrosis (13%) and various MDS entities (6%)." (PMID 32650416, 2020). "As such, loss of EZH2 function in MPN patients may provide enhanced sensitivity to BET inhibitors, which are currently in clinical testing for myelofibrosis patients." (PMID 33329600, 2020). "The loss of EZH2 led to the loss of repressive methylation of the BCAT1 promoter, leading to enhanced BCAT1 expression, sustained BCAA levels, progression of MPN (e.g., enhanced myelofibrosis) and transformation to AML." (PMID 33329600, 2020).
myelofibrosis (continued). "The prognostic scoring systems for primary myelofibrosis have evolved from phenotype driven (IPSS/DIPSS) to now include information about additional gene mutations (DIPSS-plus and MIPSS, identifying high risk molecular lesions identified as mutations in ASXL1, SRSF2, U2AF1, EZH2, IDH1 and IDH2)." (PMID 32823933, 2020). "The multivariate analysis of all parameters under study clearly showed that the presence of so-called high risk mutations in ASXL1, EZH2, IDH1/2, or SRSF2 is not able to predict progression to myelofibrosis (p = 0.99)." (PMID 33541399, 2021). "Similarly, while deletion of the EZH2 gene on its own doesn’t induce a marked phenotype in mice, crossing EZH2 knockout mice with JAK2V617F transgenic mice results in accelerated onset of myelofibrosis and marked shortening of the lifespan compared to JAK2V617F mice." (PMID 37002477, 2023).
renal carcinoma (27 papers, 2015 to 2025). A carcinoma arising from the epithelium of the renal parenchyma or the renal pelvis. "Aberrant EZH2 expression and activity have also been linked to tumorigenesis; EZH2 was found to be overexpressed in breast, prostate, and renal cancers, where its levels correlate with poor prognosis." (PMID 30890554, 2019). "Mutation or over-expression of EZH2 has been linked to many cancers including renal carcinoma." (PMID 33679454, 2021). "We constructed an EZH2 overexpression plasmid for transfection into renal cancer cell lines and verified the EZH2 overexpression efficiency." (PMID 41372608, 2025). "SF3A2 stimulates inclusion of exon 14 of the histone methyltransferase enhancer of zeste 2 polycomb repressive complex 2 subunit (EZH2) and has pro‐proliferative activity in renal cancer." (PMID 34586744, 2021). "We further provided striking evidences that knockdown of UXT inhibits proliferation, colony formation, migration and invasion of renal cancer cells, in an EZH2-dependent manner." (PMID 31481081, 2019). "Surprisingly, a most recent report shows that MALAT1 promotes the activation of PRC2 by binding to EZH2 and enhances EZH2-mediated repression of Polycomb-dependent target gene E-Cadherin in clear renal cancer." (PMID 26516927, 2015). "In contrast, a recent study reports that MALAT1 can bind to EZH2 and downregulate E-cadherin expression through EZH2-mediated H3K27me3 at the E-cadherin gene promoter in clear renal cancer." (PMID 26516927, 2015). "Furthermore, combining EZH2 inhibitors with erastin similarly promotes ferroptosis in renal cancer cells." (PMID 41372608, 2025). "Previous studies have shown that SF3B3 regulates EZH2 splicing in renal cancer and HCC." (PMID 39850359, 2025). "Moreover, the alternative splicing of EZH2 seems to have an important role in the tumorigenesis of human renal cancer." (PMID 34683129, 2021). "In vitro and in vivo studies confirmed that the abnormal increase of EZH2 can inhibit the expression level of E-cadherin, induce the epithelial stromal transformation of renal cancer cells, and promote the occurrence, development and recurrence of renal cancer." (PMID 33679454, 2021). "Our findings suggest that EZH2 may contribute to renal cancer and raise the possibility that it may be essential for the maintenance of malignant phenotypes of renal cancers." (PMID 30755832, 2019). "Since both UXT and EZH2 have been implicated in tumorigenesis, we next investigated whether UXT might regulate renal cancer tumorigenesis through modulating EZH2 HMTase activity." (PMID 31481081, 2019). "In addition, Malat1 promotes the development of renal carcinoma by interacting with Ezh2." (PMID 35309141, 2022). "In renal cancer, lncRNA HOTTIP recruits both EZH2 and LSD1 to the promoter region of LATS2 and represses LATS2 transcription by increasing H3K27me3." (PMID 33050646, 2020). "In renal cancer, MALAT1 has been shown to bind to the Enhancer of zeste homolog 2 (EZH2), a component of the histone-lysine N-methyltransferase PRC2." (PMID 31003545, 2019). "In renal cancer cells, the splicing factor SF3B3 stimulates the inclusion of exon 14 in Ezh2 transcripts." (PMID 30522506, 2018). "This phenomenon promoted aggressive RCC through Ezh2 and interacts with miR-205; this phenomenon also regulated EMT and β-catenin signaling pathways in renal cancer cells." (PMID 27527868, 2016). "Furthermore, we validated that knockdown of SPI1 combined with treatment erastin promotes renal cancer ferroptosis, elaborating on the mechanism that SPI1 interacts with EZH2 to mediate the transcriptional repression of ACSL4 targets by H3K27me3." (PMID 41372608, 2025). "By further considering well-studied oncogenes, we focused on SMAD specific E3 ubiquitin protein ligase 1 (SMURF1) and Enhancer of zeste homolog 2 (EZH2) that extensively regulate gene expression and thereby promote tumorigenesis in various carcinomas, including renal cancer." (PMID 35562342, 2022).
renal carcinoma (continued). "HOTTIP has been shown to bind EZH2 in renal carcinoma, but EZH2–HOTTIP interactions have not yet been reported in the liver." (PMID 34206504, 2021).
medulloblastoma (26 papers, 2014 to 2025). A malignant, invasive embryonal neoplasm arising from the cerebellum. "In liver and kidney malignancies, alternative EZH2 variants have been shown to contribute to tumorigenic potential; however, in medulloblastoma, which EZH2 variants are expressed and what their potential impact on the disease has not been studied." (PMID 41153744, 2025). "Taken together, these results provide the first evidence of the EZH2 mRNA variant profile in medulloblastoma, revealing the wide landscape of its expression in this disease." (PMID 41153744, 2025). "In medulloblastoma, EZH2 is highly expressed and is associated with poor prognosis." (PMID 41153744, 2025). "However, our findings revealed an association of the EZH2 RetI8 variant with deceased patients, which led us to believe that this variant could play an important role in the biology of medulloblastoma, although further studies will be necessary." (PMID 41153744, 2025). "In this work, we amplified and sequenced the most variable alternative splicing region of EZH2, revealing the EZH2 transcriptional profile in pediatric patients with medulloblastoma." (PMID 41153744, 2025). "In medulloblastoma models, phosphorylated EZH2, and its H3K27 methylation activity, were reduced upon MELK gene silencing." (PMID 38183103, 2024). "Eed-deleted and Ezh2-deleted medulloblastomas showed less apoptosis, demonstrated smaller fractions of cC3 + cells compared to control tumors, in contrast to the increased cell death that we noted in EedcKO cerebella." (PMID 36635771, 2023). "SHH medulloblastomas upregulate EZH2, the catalytic subunit of the PRC2, suggesting a growth-promoting function, and EZH2 inhibition has been proposed as a medulloblastoma therapy." (PMID 36635771, 2023). "In fact, using DZNep, an inhibitor of EZH2, was able to attenuate the proliferation of medulloblastoma cells in vitro." (PMID 37568705, 2023). "miR-101-3p mimics suppress the proliferation and migration and trigger the apoptosis of medulloblastoma cells by targeting the enhancer of zeste homolog 2 (EZH2), a histone methyltransferase." (PMID 36612314, 2023). "In the Eed-deleted and Ezh2-deleted cerebella and medulloblastomas, however, Myod1+ cells also expressed Myog and adopted a myogenic trajectory." (PMID 36635771, 2023). "Eed-deleted and Ezh2-deleted medulloblastomas both demonstrated myoid differentiation and progressed more rapidly than PRC2-intact controls." (PMID 36635771, 2023). "To determine PRC2 function in SHH medulloblastoma, we bred Eed-deleted and Ezh2-deleted mouse lines with mice genetically engineered to develop SHH medulloblastoma from CGNPs." (PMID 36635771, 2023). "The initial reduction in tumor growth in M-Smo/EedcKO tumors was consistent with previous studies that showed anti-tumor effects of PRC2 disruption using EZH2 inhibitor treatment in models SHH medulloblastoma." (PMID 36635771, 2023). "EZH2 overexpression in group 3 medulloblastoma increases H3K27me3 and impairs H3K4 methylation, thereby keeping cells in a stem-like/progenitor state." (PMID 37568705, 2023). "Medulloblastoma (MB) is the most common malignant pediatric brain tumor and is among those tumors that overexpress EZH2." (PMID 28978137, 2017). "The consistent high expression of EZH2 across different MB subgroups, and no expression of EZH2 after week 34 GSA, provides a possibility for targeted therapy with EZH2 inhibitors in medulloblastoma." (PMID 29108280, 2017). "In cancer, certain EZH2 mRNA variants are associated with tumorigenesis; however, in medulloblastoma, the alternative splicing pattern of EZH2 has not been studied." (PMID 41153744, 2025). "In medulloblastoma, EZH2 plays dual roles as a tumor suppressor and oncogene, depending on the target genes it regulates, and has been shown to be involved in the regulation of stemness features in medulloblastoma cells." (PMID 41153744, 2025).
medulloblastoma (continued). "Notably, MELK can bind to and phosphorylate EZH2 to elevate EZH2 expression, thus affecting medulloblastoma cancer stem‐like cell proliferation." (PMID 38652219, 2024). "A study on medulloblastoma found that Foxp4 and Ezh2 are both targets of the microRNA miR-101-3p, indicating the function of these genes might be linked in some scenarios." (PMID 38419656, 2024). "We investigated whether medulloblastomas with deletion of Eed or Ezh2 up-regulated the same PRC2 targets that were up-regulated in EedcKO CGNPs." (PMID 36635771, 2023). "This suggests that EZH2 inhibition can be of great potential in this subgroup; however, this needs to be further investigated using in vitro and in vivo models that specifically mimic group 4 medulloblastomas." (PMID 37568705, 2023). "However, EZH2 inactivation in an in vivo mouse model of group 3 medulloblastoma resulted instead in accelerated tumour initiation and progression, due to de-repression of the proto-oncogene Gfi1, which cooperates with Myc." (PMID 29759978, 2018). "Interestingly, chromosome X loss is seen in 80% of females with group 4 medulloblastomas Groups 3 and 4 medulloblastomas have recently been shown to have EZH2 and KDM6A alterations which are involved in histone methylation (specifically H3K27)." (PMID 25101241, 2014). "Additionally, their medulloblastoma model showed sensitivity towards tazemetostat, an EZH2 inhibitor, suggesting it may be a potential drug for Group 3 medulloblastoma patients overexpressing OTX2 and c-MYC." (PMID 36831595, 2023). "Accordingly, in medulloblastoma cells, the SHH protein has been shown to upregulate EZH2, indicating that the Sonic Hedgehog pathway plays a role in the modulation of Polycomb proteins." (PMID 39971779, 2025). "In SHH medulloblastomas, disrupting PRC2 activity through deletion of either Eed or Ezh2 was sufficient to allow widespread expression of genes typically suppressed by the PRC2, including the CDKN2A tumor suppressor." (PMID 36635771, 2023). "We show that Polycomb Repressive Complex-2 (PRC2) components EED and EZH2 maintain neural identity in cerebellar granule neuron progenitors (CGNPs) and SHH-driven medulloblastoma, a cancer of CGNPs." (PMID 36635771, 2023). "Pharmacological inhibition of EZH2 impaired proliferation and induced apoptosis of SHH medulloblastoma cells in vitro." (PMID 36671446, 2022). "In medulloblastoma, tazemetostat reactivates the expression of BAI1 by regulating EZH2 levels, thus preventing the growth of medulloblastoma cells and prolonging the survival time of the orthotopic xenotransplantation model." (PMID 34001246, 2021). "Within this review, we summarize the main preclinical studies regarding epigenetic targets (such as HDAC, SIRT, BET, EZH2, G9a, LSD1, and DNMT) inhibitors in medulloblastoma." (PMID 30560106, 2018). "Intermediate expression for EZH2 and H3K27me3 was found for SHH medulloblastoma samples, with both low and high expression of KDM6A and KDM6B." (PMID 29108280, 2017). "The histone methylases EZH2 and KDM6A represent possible future targets of these subgroups as they appear to be exclusively expressed in groups 3 and 4 medulloblastomas." (PMID 25101241, 2014). "However, in medulloblastoma (MB), EZH2 inhibition upregulated NEUROD1 and promoted cellular differentiation, highlighting the complexity of EZH2’s role in various cancer contexts." (PMID 41220942, 2025). "Importantly, in vivo models of medulloblastoma displayed a significant survival benefit from the knockdown and pharmacological inhibition of MELK and EZH2, highlighting the relevance of these two proteins in brain tumor proliferation." (PMID 38183103, 2024). "EZH2 and MELK also have a similar relationship in medulloblastoma." (PMID 38183103, 2024). "Our data show that CGNPs and medulloblastoma cells require PRC2 to maintain neural fate commitment, and that EED is specifically required for cerebellar growth, but neither EED nor EZH2 are required for medulloblastoma progression." (PMID 36635771, 2023).
medulloblastoma (continued). "In medulloblastomas, deletion of either Eed or Ezh2 resulted in myoid differentiation, but neither deletion increased apoptosis or durably prevented tumor growth." (PMID 36635771, 2023). "CDKN2A was thus up-regulated in both Eed-deleted and Ezh2-deleted medulloblastomas but did not restrict RB phosphorylation or tumor progression." (PMID 36635771, 2023). "In this study, we use mouse and human medulloblastoma stem-like cells belonging to the Sonic Hedgehog subgroup (SHH MB-SLCs) and demonstrate that genetic suppression of EZH2 reduces the level of its histone mark H3K27me3 and lowers proliferation and self-renewal." (PMID 28978137, 2017). "In this brief report, following an analysis of microarrays of medulloblastoma patients, we identify key proteins—such as LSD1, EZH2, GLI2, GLI3, and PTK7—that may serve as drug targets." (PMID 29099739, 2017).